ALB (albumin)
Diseases named in the same sentence as ALB in open-access papers (continued):
Sharing a sentence is not in itself a finding about the gene and the disease.
acute pancreatitis (continued). "Wang’s research showed that RAR had a higher AUC for predicting severe acute pancreatitis compared to RDW or albumin." (PMID 39919086, 2025). "By doing so, we aim to justify the benefit of using serum albumin levels in early prognostic assessment and to contribute to the evidence-based clinical practice regarding biomarker-guided management in acute pancreatitis." (PMID 41523521, 2025). "Accordingly, this meta-analysis was done to assess the association between serum albumin level and AKI in patients with acute pancreatitis." (PMID 41523521, 2025). "This systematic review and meta-analysis demonstrates that elevated red blood cell distribution width-to-albumin ratio (RAR) is significantly associated with increased mortality and severity in patients with acute pancreatitis." (PMID 40291314, 2025). "In acute pancreatitis, systemic inflammation and increased capillary permeability drive albumin leakage from the intravascular to the interstitial space, further lowering plasma concentrations." (PMID 41523521, 2025). "This study aimed to investigate the correlation between the serum urea nitrogen-to-albumin ratio (BAR) and the mortality risk in ICU patients with acute pancreatitis." (PMID 40971376, 2025). "In light of this, we are conducting a systematic review of the studies that aimed to investigate the association between serum albumin levels and AKI in patients admitted with acute pancreatitis." (PMID 41523521, 2025). "This study aimed to assess the significance of serum albumin levels within 24 h of patient admission in correlation with the incidence of outcomes and mortality in patients diagnosed with acute pancreatitis." (PMID 39048942, 2024). "Serum creatinine (Cr) and albumin (Alb) are important predictors of mortality in individuals with various diseases, including acute pancreatitis (AP)." (PMID 38686375, 2024). "Pain score, serum creatinine, hematocrit, serum calcium, and serum albumin were independent predictors of acute pancreatitis complicated by persistent organ failure." (PMID 39165374, 2024). "In conclusion, serum albumin levels within 24 h of patient admission appear to be a significant prognostic biomarker in acute pancreatitis, particularly in anticipating persistent organ failure and mortality." (PMID 39048942, 2024). "The decrease in circulating albumin, coupled with heightened inflammation in Ehmt2fl/fl mice, suggests a potential increase in capillary permeability and the efflux of circulating albumin into interstitial spaces, which is seen in cases of acute pancreatitis." (PMID 38948355, 2024). "This prospective observational study demonstrates that the CRP/albumin ratio, calculated within 24 hours of admission, can reliably predict persistent organ failure in acute pancreatitis." (PMID 38283464, 2023). "This shows the CRP/albumin ratio was significantly higher in severe AP; mild acute pancreatitis: 60 (40%); moderate acute pancreatitis: 16 (11%); severe acute pancreatitis: 74 (49%)." (PMID 38283464, 2023). "This study demonstrates the CRP/albumin ratio calculated within 24 hours of admission as a promising prognostic marker for predicting persistent organ failure in acute pancreatitis in the Indian population." (PMID 38283464, 2023). "The CRP/albumin ratio demonstrated superior predictive performance for severe acute pancreatitis compared to the conventional Ranson scoring system in our study." (PMID 38283464, 2023). "Patients with severe acute pancreatitis (SAP) were significantly older, more likely to be female, and had higher CRP levels, lower albumin, and higher CRP/albumin ratios compared to mild acute pancreatitis patients." (PMID 38283464, 2023). "This indicates that the CRP/albumin ratio has a good discriminative ability to distinguish between mild and severe acute pancreatitis." (PMID 38283464, 2023).
acute pancreatitis (continued). "In general, our research is the first clinical investigation concentrating on the role of human serum albumin infusion in the hospital outcomes of patients diagnosed with acute pancreatitis since 2008." (PMID 35721190, 2022). "The entire study cohort included 950 patients diagnosed with acute pancreatitis between 2008 and 2019, of whom 228 received human serum albumin infusion during hospitalization (Alb group), and the remaining did not (non-Alb group)." (PMID 35721190, 2022). "A systematic review of the literature was performed using the keywords CRP albumin ratio and acute pancreatitis in the PubMed and Cochrane databases." (PMID 36262941, 2022). "A positive correlation was found between the CRP/albumin ratio at admission and the development of subsequent severe acute pancreatitis in these studies." (PMID 36262941, 2022). "In the current study, we aimed to evaluate the effectiveness of the red cell distribution width/albumin ratio (RAR) in determining the severity of acute biliary pancreatitis (ABP)." (PMID 36238420, 2022). "Our systematic review has shown a positive correlation was found between the CRP/albumin ratio at admission and the development of subsequent severe acute pancreatitis, increased hospital length of stay, and higher rate of mortality in these studies." (PMID 36262941, 2022). "Serum albumin has been found predictive of persistent organ failure in acute pancreatitis in multiple studies; and in our analysis it was linked to infected pancreatic necrosis as well." (PMID 36057565, 2022). "Overall, a positive correlation was found between the CRP/albumin ratio at admission and the development of subsequent severe acute pancreatitis, increased hospital length of stay, and the higher rate of mortality in these studies." (PMID 36262941, 2022). "In our review, across three studies, we identified 956 patients with acute pancreatitis that were enrolled in studies that examined the relationship of the CRP/albumin ratio with the severity of acute pancreatitis." (PMID 36262941, 2022). "Previous studies have shown CRP/albumin ratio as an important prognostic marker in acute pancreatitis." (PMID 36268355, 2022). "While, one study conducted on animals determined role of CRP/albumin ratio in survival of acute pancreatitis." (PMID 36268355, 2022). "Even accounting for other inflammatory markers like Ferritin, CRP/albumin ratio stands out in predicting severity of the disease and mortality in acute pancreatitis." (PMID 36268355, 2022). "Lastly, CRP/albumin ratio was considered a good prognostic marker in predicting severe acute pancreatitis with significantly moderate correlations with all severity scores and hospitalization period." (PMID 36268355, 2022). "In contrast, the level of albumin, the incidence rate of acute pancreatitis and the length of hospital stay were higher in survivors group (all p < 0.05)." (PMID 36577937, 2022). "Reduced albumin and elevated α2-globulin are characteristic features of acute phase response, as described in our previous study on canine acute pancreatitis." (PMID 33732740, 2021). "High levels of NLR, RDW, glucose, and CRP at the first admission in the emergency department appear to be associated with an increased hospital stay, increased NLR, PLR, glucose, and CRP values low albumin values in acute pancreatitis." (PMID 33489590, 2020). "Increases in the levels of serum C-reactive protein (CRP) and creatinine (Cr) and decreases in those of albumin (Alb) are commonly observed in acute pancreatitis (AP)." (PMID 33298030, 2020). "In our study, a statistically significant result was found between low albumin levels in blood values obtained at first admission and one-year mortality in patients diagnosed with acute pancreatitis in the emergency department (p <0.001)." (PMID 33489590, 2020). "A few reports have also attempted to study the effect of serum albumin levels on the clinical outcomes of acute pancreatitis." (PMID 29147647, 2017).
acute pancreatitis (continued). "We designed our research according to 2012 revision of the Atlanta Classification of acute pancreatitis, and we found the level of albumin in acute pancreatitis patients with POF is much lower than patients without POF." (PMID 28446147, 2017). "Serum calcium and albumin-corrected calcium obtained within the first 24 hours of hospital admission are useful predictors of severity in acute pancreatitis." (PMID 29410978, 2017). "Additionally, the machine learning results suggested that the serum urea nitrogen to albumin ratio is an important feature for the outcomes of severe acute pancreatitis." (PMID 40971376, 2025). "The search strategy combined terms related to acute pancreatitis (e.g., "acute pancreatitis," "pancreatitis," and "pancreatic inflammation") and red blood cell distribution width-to-albumin ratio (e.g., "red cell distribution width," "RDW," "albumin," "RDW/Alb ratio," and "RAR")." (PMID 40291314, 2025). "CRP, calcium, and albumin are predictive factors for severe acute pancreatitis." (PMID 38459563, 2024). "The reduction in albumin, along with diminished total protein levels in Ehmt2fl/fl serum implies a potential impairment in liver and/or kidney function, frequently observed during acute pancreatitis episodes in humans." (PMID 38948355, 2024). "We believe the CRP/albumin ratio is easy to calculate and gauge the severity of acute pancreatitis." (PMID 36262941, 2022). "This phenomenon might be explained by the body’s self-compensation mechanism, suggesting that albumin infusion might be even more discouraged in acute pancreatitis patients with albumin levels near normal." (PMID 35721190, 2022). "There is sparse literature on evaluating the role of the CRP/albumin ratio in acute pancreatitis." (PMID 36262941, 2022). "The CRP/albumin ratio has been shown as a predictor of mortality in acute pancreatitis patients." (PMID 30297655, 2018). "Similarly, ROC curve of albumin-corrected calcium analyzed for severe acute pancreatitis showed AUC of 0.781, which was also significant (p value: 0.002)." (PMID 29410978, 2017). "We identified serum albumin predictive to persistent organ failure in acute pancreatitis." (PMID 28446147, 2017). "Moreover, combining serum albumin with other biomarkers may also enhance their predictive accuracy for early AKI prediction in acute pancreatitis." (PMID 41523521, 2025). "In order to meet the body’s needs, the body breaks down albumin to provide amino acids for processes such as gluconeogenesis, providing energy for immune cells and other cells in the inflammatory response, which in turn aggravates inflammation and leads to the development of acute pancreatitis." (PMID 39771144, 2024). "CRP/albumin ratio could be used to predict prognosis in patients with acute pancreatitis." (PMID 36262941, 2022). "However, the actual association between human serum albumin infusion and acute pancreatitis patients’ prognosis has not been confirmed by clinical studies so far." (PMID 35721190, 2022). "In conclusion, intravenous human serum albumin infusion could not benefit acute pancreatitis patients’ in-hospital prognosis and was associated with prolonged hospital and ICU duration." (PMID 35721190, 2022). "Therefore, the aim of this study was to investigate whether serum albumin levels within 24 hrs of patient admission correlate with clinical outcomes in acute pancreatitis." (PMID 29147647, 2017). "ROC curve was plotted to assess the predictive values of BAR level, serum BUN, albumin, and SAPS II for 28-day and 90-day mortality in acute pancreatitis." (PMID 41171733, 2025). "The aim of the paper was to study the effectiveness of individualized comprehensive nutritional support on inflammatory markers, serum amylase (AMS), prealbumin (PA), albumin (ALB), calcium ion (Ca2+) in patients with severe acute pancreatitis (SAP)." (PMID 39980616, 2024).
acute pancreatitis (continued). "However, few studies have determined which factors might relate to a longer length of stay of patients with acute pancreatitis except for those with a higher severity score using the revised Atlanta classification and some biomarkers such as the C reactive protein/albumin ratio." (PMID 38248369, 2024). "In our review, across these three studies, 956 patients with acute pancreatitis were identified and enrolled in studies that examined the relationship between the CRP/Albumin ratio and the severity of acute pancreatitis." (PMID 36262941, 2022). "Early patient stratification according to the potential severity is of paramount importance in acute pancreatitis; hence, more studies are needed to assess the utility of the CRP/albumin ratio as a prognostic tool." (PMID 36262941, 2022). "•There is a need to diagnose the severity of acute pancreatitis using a single test ratio i.e., CRP/albumin ratio." (PMID 36268355, 2022). "The rationale of this study is to diagnose the severity of acute pancreatitis using a single test ratio, i.e., CRP/albumin ratio which is a combination of markers for systemic inflammation and nutritional status." (PMID 36268355, 2022). "In this study, we aimed to evaluate the red cell distribution width (RDW)/albumin ratio (RAR), which, we consider, can be used to determine the clinical course of acute biliary pancreatitis (ABP)." (PMID 36238420, 2022). "Then, CAR became a novel inflammation marker with predictive value in patients with acute pancreatitis and active Crohn’s disease; it was believed to more specific than CRP or albumin alone." (PMID 34726101, 2021). "The association between red blood cell distribution width-to-albumin (RDW/ALB) ratio (RAR) and all-cause mortality in patients with acute pancreatitis has not been fully delineated." (PMID 39919086, 2025). "According to our results, albumin administration did not influence the primary outcome of patients with acute pancreatitis in either infusion volume subgroup." (PMID 35721190, 2022). "With the ever-evolving use of the acute-phase reactant protein, C-reactive protein (CRP), and an abundant circulating protein in plasma, albumin, in daily practice, this study aimed to assess the ratio of CRP and albumin for assessing the severity of acute pancreatitis." (PMID 36262941, 2022). "This is not unexpected because albumin is a known negative acute phase protein that decreases with acute inflammation, including acute pancreatitis." (PMID 34250650, 2021). "In line with this, a short half-life of only 3.5 days was measured for cleaved albumin lacking L585 in a patient with acute pancreatitis." (PMID 32313072, 2020). "At present, the relationship between severe acute pancreatitis (SAP) and albumin infusion is not clear." (PMID 37277756, 2023).
Hypercalcemia (81 papers, 2008 to 2026). An abnormally increased calcium concentration in the blood. "It is important to monitor albumin-adjusted calcium concentrations frequently during pregnancy and adjust supplementation as needed because maternal hypo- and hypercalcemia are associated with complications including fetal morbidity and death." (PMID 37335755, 2023). "Acidosis decreases calcium binding to albumin thus increasing the levels of ionized calcium, which can cause life threatening hypercalcaemia, hence it is important to maintain normocarbia." (PMID 20640216, 2009). "Hypercalcemia is associated with pruritus in most studies, while some evidence show opposite conclusion, possibly influenced by albumin." (PMID 40630124, 2025). "A decrease in serum albumin levels may increase the “free” fraction of serum calcium; however, parathyroid-related protein (PTHrP), the major cause of malignancy-induced hypercalcemia, is more likely to contribute to the increase in serum calcium levels." (PMID 39764412, 2024). "However, further evaluation unveiled a persistent serum protein gap, hypercalcemia, and significant non-albumin proteinuria, prompting a more comprehensive diagnostic approach." (PMID 37779736, 2023). "Importantly, the association of hypercalcemia with infection-related death was enhanced in patients with lower serum albumin level and in younger patients." (PMID 32286455, 2020). "The pathogenesis of calciphylaxis is unknown, however, several risk factors have been identified such as hypercalcemia, hyperphosphatemia, hyperparathyroidism, low serum albumin, and history of warfarin therapy." (PMID 33391959, 2020). "During admission, she developed acute confusion and was found to have severe hypercalcemia (albumin-corrected calcium 3.7 mmol/L) with suppressed parathyroid hormone (PTH) and elevated parathyroid hormone-related protein (PTHrP)." (PMID 42281681, 2026). "Our MM patients who experienced VTE had a higher disease burden at diagnosis, evidenced by lower Hb levels, reduced serum albumin, elevated β2-microglobulin, hypercalcemia, and increased lactate dehydrogenase (LDH) levels." (PMID 39941428, 2025). "Hypercalcemia at diagnosis was defined as an albumin‐corrected serum calcium level > 2.6 mmol/L, equivalent to 10.4 mg/dL." (PMID 40067281, 2025). "Laboratory investigations revealed marked hypercalcemia with an ionized calcium concentration of 1.78 mmol/L and a total calcium unadjusted for albumin level of 3.76 mmol/L (15.3 mg/dl)." (PMID 40547129, 2025). "Laboratory evaluation revealed hypercalcemia (ionized calcium 1.49 mmol/L; total plasma calcium unadjusted for albumin 2.81 mmol/L, 11.4 mg/dl), suppressed PTH (<1 pmol/L) and reduced 1,25-dihydroxyvitamin D (<12 pmol/L)." (PMID 40547129, 2025). "The median calcium concentration was 3.3 mmol/L (3.1–3.7), the median albumin-adjusted calcium concentration was 3.3 mmol/L (3.1–3.6), and 34 patients had severe hypercalcaemia (Ca > 3.5 mmol/L)." (PMID 39804184, 2025). "Recurrence is defined as hypercalcaemia (serum calcium adjusted for albumin ≥2.6 mmol/L) occurring after six months of eucalcaemia (serum calcium adjusted for albumin in the range of 2.2-2.6 mmol/L) post seemingly corrective parathyroidectomy." (PMID 38449925, 2024). "A total of 37 patients (97.37%) had hypercalcaemia pre-operatively (defined as serum calcium adjusted for albumin ≥ 2.6 mmol/L) with a mean calcium value of 2.82 mmol/L (range 2.45 to 3.22 mmol/L)." (PMID 38449925, 2024). "The new formula based on albumin and globulin was developed, which was verified to be better than the traditional formula for correctly diagnosing hypercalcemia." (PMID 39544294, 2024). "Among all of the patients, 21 (19%) were diagnosed with hypercalcemia according to albumin-corrected calcium." (PMID 39544294, 2024). "Six months later, blood tests revealed disease recurrence with PTH-dependent hypercalcemia (albumin-corrected calcium 2.74 mmol/L [10.98 mg/dL], PTH 14.5 pmol/L [136.8 pg/mL])." (PMID 39011405, 2024).